PON1 (paraoxonase 1)
Diseases named in the same sentence as PON1 in open-access papers (continued):
Sharing a sentence is not in itself a finding about the gene and the disease.
Sepsis (26 papers, 2010 to 2025). Sepsis is defined as life-threatening organ dysfunction caused by a dysregulated host response to infection. "Paraoxonase 1 (PON1), negatively associated with higher mortality of sepsis, underlines significance in ARDS pathology compared to DC and HC groups." (PMID 38956604, 2024). "SAA3, CXCL9, and Orm1 are induced by pulmonary inflammation, while Pon1 is associated with oxidative stress in sepsis caused by MRSA (40, –, 43)." (PMID 38323827, 2024). "Short-time survival in sepsis is strongly associated with its initial severity, as already mentioned; admission as well as mean PON1 was substantially lower in septic shock." (PMID 30886652, 2019). "So far, PON1 suitability as a diagnostic marker in sepsis has been evaluated only for enzyme paraoxonase and diazoxonase activities and yielded similar results with excellent and good accuracy, respectively." (PMID 30886652, 2019). "Indeed, although not correlated with either of the clinical scores, we showed PON1 activity to be significantly more reduced in septic shock than severe sepsis, thus demonstrating its association with condition severity." (PMID 30886652, 2019). "Low PON1 activity was associated with higher mortality of surgical patients with sepsis." (PMID 24665146, 2014). "Therefore, in natural situations, where the extent and severity of inflammation are very variable, PON-1 might prove to be useful as a diagnostic or prognostic marker of sepsis." (PMID 33148245, 2020). "The alpha-trypsin inhibitor ITIH3 has been described in sepsis as well as to be related to mortality in severe COVID-19 and the activity of the serum paraoxonase PON1 has been shown to be predictive for 30-day mortality." (PMID 40898225, 2025). "Low blood levels of paraoxonase-1 (PON-1) are associated with more severe symptoms in patients with viral hepatitis and poor survival in patients with severe sepsis." (PMID 35409326, 2022). "The antioxidant potential of HDL is also compromised in sepsis, since the arylesterase activity and paraoxonase activity of HDL-associated paraoxonase 1 (PON1) are reduced in patients with sepsis." (PMID 36361756, 2022). "We aimed to assess the accuracy of C-Reactive Protein (CRP), protein carbonyls (PCO) and paraoxonase-1 (PON1) in differentiating dogs with sepsis from those with sterile inflammation and healthy ones, and predict the outcome in septic dogs." (PMID 34072427, 2021). "Ultimately, evaluation of CRP and PON1 at admission seems a reliable support to diagnose sepsis and predict outcomes." (PMID 34072427, 2021). "The same differences were found when only results from dogs with sepsis or trauma were compared to each other, although the level of significance was lower than in the previous comparison for PON1 (p < 0.05)." (PMID 34072427, 2021). "HDL is a major source of cholesterol for endogenous corticosteroid production in the adrenal glands, and prevents tissue damage in sepsis, a function mediated by several of HDLs proteins including paraoxonase-1 (PON-1) and apolipoprotein A-I (Apo A-I)." (PMID 34018068, 2021). "PON-1 has an established role in modulating oxidative stress, which is a major promoter and mediator of the systemic inflammatory response occurring in sepsis." (PMID 33148245, 2020). "With the reduction in plasma PAF-AH and PON1 activities during sepsis, HDLs display blunted protective effects against LDL oxidation." (PMID 32264946, 2020). "In particular, several studies have highlighted the potential of PON-1 in the pathogenesis, diagnosis and prediction of outcome in naturally occurring and experimentally induced sepsis in many species, including horses." (PMID 33148245, 2020). "According to our results, plasma iron concentration appears to be an earlier marker of sepsis onset and positive resolution compared to PON-1 activity." (PMID 33148245, 2020). "On the other hand, sepsis patients compared to ICU controls had decreased AEA of PON1 (67 compared to 111 mM/min/ml serum)." (PMID 33195328, 2020).
Sepsis (continued). "Despite potential relevance of PON1 for sepsis development and progression, data on the enzyme status in sepsis remains scanty." (PMID 30886652, 2019). "As a multifunctional enzyme, which anti-inflammatory, antioxidant, and quorum-sensing activities are potentially relevant for sepsis development, PON1 arouses special interest." (PMID 30886652, 2019). "Paraoxonase-1 (PON1) is a serum-based antioxidant, anti-inflammatory agent, detoxifier, and quorum-sensing factor found to be a prognostic marker in sepsis." (PMID 30886652, 2019). "PON1 activity remained lower in septic shock as compared to severe sepsis following adjustment to patients' age (p = 0.027)." (PMID 30886652, 2019). "PON1 activities on admission to ICU had good to excellent capacity to differentiate surgical patients with sepsis from healthy controls." (PMID 24665146, 2014). "Previous studies showed low PON1 activity in small groups of medical patients with sepsis compared to healthy controls." (PMID 24665146, 2014). "This study demonstrated significantly lower PON1 activity in surgical patients with sepsis than in healthy controls." (PMID 24665146, 2014). "The objective of this study was to investigate PON1 activity in surgical patients with sepsis in relation to disease severity, oxidative stress status, inflammation, and survival." (PMID 24665146, 2014). "We investigated PON1 activity in surgical patients with sepsis in relation to oxidative stress status, inflammation, disease severity, and survival." (PMID 24665146, 2014). "This function of apoM is likely impaired during the sepsis, which would add to the decreased antioxidative capacity of HDL that is additionally caused by the decrease in PON-1 levels." (PMID 22512779, 2012). "In the present study, serum PON1 activity significantly decreased in patients with acute viral hepatitis, sepsis with multi organ failure and falciparum malaria." (PMID 20339175, 2010). "PON1 activity has decreased significantly in acute viral hepatitis, sepsis with multi organ failure and falciparum malaria patients." (PMID 20339175, 2010). "In conclusion, PON1 activity has decreased significantly in acute viral hepatitis, sepsis with multi organ failure and falciparum malaria patients." (PMID 20339175, 2010). "PON1 activity significantly decreased in viral hepatitis (P<0.001) and sepsis (P<0.001) and moderately in falciparum malaria patients (P<0.001)." (PMID 20339175, 2010). "The serum PON1 activity in patients with acute viral hepatitis and sepsis decreased significantly (P<0.001) and moderately in falciparum malaria (P<0.05)." (PMID 20339175, 2010). "On applying Pearson correlation, serum PON1 activity correlated positively with HDL-C in patients with sepsis (r=0.633, P<0.05), left ventricular failure patients (r=0.814, P<0.05) and negatively with acute viral hepatitis patients (r=– 0.528, P<0.05)." (PMID 20339175, 2010). "Interestingly, in sepsis patients, the AE-activity of PON1 was suggested as an independent predictor of 28-day and ICU mortality in multivariable analyses." (PMID 36290581, 2022). "In our opinion, measurement of CRP and PON1 could be an advisable tool to support a clinical diagnosis of sepsis and predict the outcome in routine practice." (PMID 34072427, 2021). "Here, we demonstrated that a Hypolipoprotein phenotype of sepsis, represented by lower levels of HDL-C, ApoA-I, and reduced PON-1 activity is associated with increased endothelial dysfunction, organ failure, and poorer outcomes compared to a Normolipoprotein phenotype." (PMID 34535154, 2021). "Similarly, PON1 activity was significantly lower in dogs with sepsis than in dogs with trauma and in clinically healthy dogs, and a significant difference was found also between dogs with trauma and clinically healthy dogs." (PMID 34072427, 2021).
Sepsis (continued). "On the contrary, the decrease of PON1 activity, which depends on a more complex mechanism involving decreased hepatic production and displacement of circulating PON1 from oxidized lipoproteins, seems to occur only when inflammation is more severe, as it usually happens in sepsis." (PMID 34072427, 2021). "The oxidative environment induced by sepsis could result in an increased binding of free radicals to PON-1, leading to an overall decreased plasma activity of this enzyme." (PMID 32264946, 2020). "Sepsis caused by MRSA may contribute to an oxidative environment, which may result in increased binding of free radicals to PON1, leading to a reduction in PON1 activity in the circulation." (PMID 32718325, 2020). "We also aimed to evaluate PON1 suitability as a biomarker in sepsis." (PMID 30886652, 2019). "Nevertheless, while indicative of strength of association, the excellence of PON1 in discriminating sepsis patients from healthy individuals is unlikely to find an application in clinical practice." (PMID 30886652, 2019). "MODS was associated with decreased PON1, more so in patients with septic shock, displaying an excellent accuracy as a marker of MODS (91%) and a fair one as a marker in differentiating septic shock from severe sepsis (76%)." (PMID 30886652, 2019). "PON1 activity has been found to decrease more pronouncedly in sepsis nonsurvivors, and a drop in its associated activity reduces the overall survival or higher risk of death." (PMID 30886652, 2019). "Further studies are needed to fully investigate role of PON1 in pathogenesis of sepsis." (PMID 24665146, 2014). "AUC-ROC was used to evaluate PON1 activities on admission to ICU as a marker of sepsis." (PMID 24665146, 2014). "On applying Pearson correlation, serum PON1 activity correlated positively with high-density lipoprotein-cholesterol (HDL-C) in patients with sepsis (r=0.633, P<0.05), left ventricular failure patients (r=0.814, P<0.05) and negatively with acute viral hepatitis patients (r=– 0.528, P<0.05)." (PMID 20339175, 2010). "Moreover, PON1 also hydrolyzes phosphatidylcholines into lysophosphatidylcholines, which improve the bactericidal activity of neutrophils potentially resulting in a protective effect in experimental sepsis." (PMID 32264946, 2020). "Similarly, the activity of PON1 in MODS patients with sepsis other than abdominal tended to increase whereas this in patients with abdominal sepsis decreased, so the difference in PON1 observed at admission lost its significance already on the 2nd day (p = 0.086)." (PMID 30886652, 2019). "A relationship between changes in PON1 status and MCP-1 concentrations has also been shown in patients with severe sepsis." (PMID 40867910, 2025). "In conclusion, these results confirm that oxidation is present during inflammatory conditions and especially in sepsis and support the role of CRP and PON1 in confirming a clinical diagnosis of sepsis." (PMID 34072427, 2021). "In order to evaluate PON1 suitability in this capacity, we assessed PON1 power in differentiating MODS patients with septic shock and severe sepsis and found it to be fair." (PMID 30886652, 2019). "Plasma levels of anti-inflammatory apolipoprotein A-I (apoA-I), the major protein constituent of HDL, and anti-oxidant enzyme paraoxonase 1 (PON1), are also reduced by sepsis." (PMID 23691230, 2013). "PON1 and CRP were, respectively, significantly lower and higher in dogs with sepsis compared with polytraumatized and clinically healthy dogs (p < 0.001 for both the analytes), and also in dogs with trauma compared with healthy dogs (p = 0.011 and p = 0.017, respectively)." (PMID 34072427, 2021). "Therefore, the caseload included also a low number of dogs on which the diagnosis of sepsis was presumed on the basis of the final diagnosis and/or on the presence of changes in inflammatory markers of inflammation such as CRP and/or PON-1." (PMID 33363227, 2020).
Sepsis (continued). "The simultaneous decrease in PON-1 activity and recovery from clinical signs is in contrast with those studies that in humans reported PON-1 increase when patients with naturally occurred sepsis clinically improved." (PMID 33148245, 2020). "Moreover, paraoxonase-1 (PON-1), an enzyme located in HDL inhibiting lipoprotein oxidation in LDL, which is reduced in adult sepsis, appeared significantly lower in septic newborns before treatment in comparison to controls and also to posttreatment levels." (PMID 30174784, 2018). "So far, no data have been reported on the utility of serial PON1 measurement in surgical patients with sepsis." (PMID 24665146, 2014). "Ultimately, the comparison of results of CRP, PCO and PON1 confirm the hypothesis that in dogs with sepsis, oxidative phenomena are stronger than in dogs with non-septic inflammation, as already demonstrated for people." (PMID 34072427, 2021). "Hence, moderate increases of CRP or moderate decreases of PON1 may not differentiate dogs with sepsis from dogs with non-septic conditions." (PMID 34072427, 2021). "PON1 activity was constantly low throughout the whole course of observation in patients with CVI and septic shock but steadily decreased in patients without CVI and with severe sepsis." (PMID 30886652, 2019). "All published studies on PON1 unambiguously and unanimously indicate its diminished activity in sepsis as compared to both healthy individuals and ICU patients without sepsis as well as the enzyme restoration during recovery." (PMID 30886652, 2019). "Moreover, the measurement of PON1 and CRP at admission, but not of PCO, may predict the possible outcome of dogs with sepsis." (PMID 34072427, 2021).
COVID-19 (24 papers, 2021 to 2025). A disease caused by infection with severe acute respiratory syndrome coronavirus 2. "Naturally, severe acute respiratory syndrome coronavirus-2 (SARS-CoV-2) which causes COVID-19 has become a subject of extensive research worldwide, and some studies focused also on PON1 activity in the context of this disease." (PMID 36833509, 2023). "Another cause that may explain the decrease in PON1 activity is that the composition of high-density lipoproteins is altered in COVID-19, with a decrease in cholesterol content and an increase in serum amyloid A." (PMID 35883435, 2022). "Additionally, we were unable to assess certain properties of HDL in our study, such as Serum amyloid-A enrichment or paraoxonase-1 activity, which have been shown to be associated with COVID-19 even in the early stages of infection." (PMID 35843172, 2022). "A large study of 615 COVID-19 patients showed that serum PON1 arylesterase activity was significantly decreased in those with COVID-19 compared to HCs (PON1 activity ∼120 U/L vs. ∼213 U/L; p < 0.001)." (PMID 41209585, 2025). "Serum PON1 activity is markedly decreased in COVID-19, especially in patients with comorbidities such as diabetes or cardiovascular disease, and the measurement of the serum levels of this enzyme has been proposed as a diagnostic marker." (PMID 40723899, 2025). "Variants such as SOD2 rs4880, GSTP1, GSTO1, PON1, and NOS3 have been associated with reduced enzymatic activity, impaired detoxification of ROS, and worsened COVID-19 severity or post-acute sequelae." (PMID 41209585, 2025). "Among the dysregulated metabolic enzymes, high levels of the antioxidant protein PON1 were found both in COVID-19 patients with comorbidities and patients with early infections in this study." (PMID 38672194, 2024). "It has already been shown that in COVID-19 patients, apoA-I and PON1 are less abundant, whereas the content of SAA and alpha-1 antitrypsin was higher." (PMID 36290581, 2022). "In the present study, we aimed to investigate the usefulness of serum arylesterase activity of PON1 measurement in the evaluation of COVID-19 in a larger series of outpatients and hospitalized patients, with different levels of disease severity." (PMID 35883435, 2022). "Serum PON1 arylesterase activity was 120.3 (59.5–176.1) U/L in COVID-19-positive patients and 213.3 (141.8–436.3) U/L in the healthy subjects (p < 0.001)." (PMID 35883435, 2022). "Among these mechanisms, the enzyme paraoxonase-1 (PON1) plays an important role and a recent study by our research group has shown that PON1 activity is greatly inhibited in the serum of COVID-19 patients." (PMID 35740079, 2022). "A previous study by our research group showed that serum PON1 activity is decreased, and its concentration is increased in patients with COVID-19." (PMID 35740079, 2022). "Results showed PON1 activity greatly decreased in COVID-19 compared to healthy volunteers; a receiver operating characteristics plot showed a high diagnostic accuracy." (PMID 35883435, 2022). "We recently reported preliminary results suggesting that the measurement of paraoxonase-1 (PON1) arylesterase activity can be a good marker of COVID-19, with excellent sensitivity and specificity." (PMID 35883435, 2022). "The ROC curve showed that PON1 measurement was unable to segregate COVID-19-positive patients from subjects with the other diseases in the study group." (PMID 35883435, 2022). "Such profound modifications of HDL proteome are also associated with the loss of the antioxidative enzyme PON1, which ultimately leads to HDL dysfunction, as seen in cardiometabolic and malignant diseases but also in COVID-19." (PMID 36420478, 2022). "HDL from COVID-19 individuals with decreased levels of Apo A-1 and paraoxonase 1(PON) proteins shows compromised anti-apoptotic activity as compared to native HDL from non-COVID-19 controls." (PMID 35999545, 2022).